RNU6-190P (RNA, U6 small nuclear 190, pseudogene)
Gene: Small nuclear RNA gene on chromosome 6 (17,619,533 to 17,619,634, forward strand). Ensembl gene ENSG00000206881.
Homologues: Orthologues: chimpanzee U6 (100% identical), macaque U6 (96% identical). Paralogues in human: RNU6-21P (87% identical), RNU6-144P (86% identical), RNU6-16P (86% identical), RNU6-33P (86% identical), RNU6-480P (86% identical), RNU6-1 (85% identical), RNU6-1011P (85% identical), RNU6-140P (85% identical), RNU6-15P (85% identical), RNU6-2 (85% identical), RNU6-38P (85% identical), RNU6-39P (85% identical), and 1288 more.